BMAL1 (basic helix-loop-helix ARNT like 1)
Diseases named in the same sentence as BMAL1 in open-access papers (continued):
Sharing a sentence is not in itself a finding about the gene and the disease.
psychiatric disorder (13 papers, 2010 to 2025). A disorder characterized by behavioral and/or psychological abnormalities, often accompanied by physical symptoms. "We investigated the BMAL1 locus genetic variants for associations with both cardiometabolic and mental illness." (PMID 39667926, 2024). "The link between D2R signaling and BMAL1 stability is challenging, as dopamine dysfunctions underlie neurological and psychiatric disorders which are disruptive of the circadian clock." (PMID 20049328, 2010). "The BMAL1 gene is associated with many psychiatric disorders." (PMID 40646562, 2025). "These diverse lines of evidence suggest that Bmal1 may play a causative role in mental disorders, some of which phenotypically resemble neurological disorders." (PMID 36593479, 2023). "To explore the role of BMAL1 specifically in dopaminergic neurons and its implications for psychiatric disorders, we generated mice with conditional knockout of Bmal1 to investigate the underlying mechanisms." (PMID 40646562, 2025). "Among these components, Bmal1 acts as a key generator of the circadian clock, and global knockout of BMAL1 in rodents or monkeys leads to abnormal rhythmic behaviors and psychiatric disorders." (PMID 40646562, 2025). "Our study aimed to describe the genetic architecture of the BMAL1 locus, a regulator of circadian rhythm, in relation to psychiatric disorders, psychological/behavioural phenotypes and cardiometabolic diseases." (PMID 39667926, 2024). "We identified associations between genetic variation in BMAL1 and cardiometabolic (HbA1c, DBP, SBP, ever smoking, BMI and WHR) and mental illness phenotypes (anhedonia, MDD, risk-taking behaviour and neuroticism)." (PMID 39667926, 2024). "Overall, Bmal1 may be responsible for the onset and progression of several psychiatric disorders through multiple pathways." (PMID 36593479, 2023). "This study systematically investigated common genetic variation in the BMAL1 locus a range of phenotypes, to assess whether this circadian rhythm gene might represent a biological mechanism linking mental illness to cardiometabolic diseases, using data from the UKB population study." (PMID 39667926, 2024). "Thus, BMAL1 knockout monkeys are potentially useful for studying the physiological consequences of circadian disturbance, and for developing therapies for circadian and psychiatric disorders." (PMID 34691834, 2019).
neurodegenerative disease (10 papers, 2020 to 2025). A disorder of the central nervous system characterized by gradual and progressive loss of neural tissue and neurologic function. "Melatonin can exhibit its effects regarding alleviating circadian disruption through regulation of related clock genes including PER1 and BMAL1, which have been confirmed to be associated with the development of neurodegenerative diseases." (PMID 34557221, 2021). "Melatonin increases the expression levels of cryptochrome 2 (CRY2), period circadian protein homologue 1 (PER1) and brain muscle ARNT-like 1 (BMAL1), which are associated with neurodegenerative diseases." (PMID 32784556, 2020). "In summary, BMAL1 is implicated in neurodegenerative diseases through distinct mechanisms." (PMID 41440117, 2025). "Loss of Bmal1 in astrocytes was demonstrated to promote neuronal death due to aging and neurodegenerative diseases through the regulation of astrogliosis in a synergistic manner by a cell-autonomous mechanism and a lesser non-cell-autonomous signal from neurons." (PMID 34557221, 2021). "Tea polyphenols contain powerful antioxidant properties and ameliorate mitochondrial dysfunction in a Bmal1‐dependent manner, playing an important role in the recovery of neurodegenerative diseases." (PMID 36056774, 2022). "Further study into the cell- and model-dependent effects of Bmal1 and other clock genes is needed to fully understand how core clock disruption may influence neurodegenerative diseases." (PMID 38032732, 2024). "Thus, future work should evaluate Bmal1 knockout microglial function and neuronal changes in mice under different stressful conditions, such as LPS and high-fat diet, or in combination with neurodegenerative diseases." (PMID 33363534, 2020).
cardiovascular diseases (8 papers, 2020 to 2024). "A number of studies reported that mutations in core circadian gene BMAL1 or its partner CLOCK tended to develop cardiovascular diseases." (PMID 32277346, 2020). "Since PAI-1 expression peaks at 6 am, and it has been shown that CLOCK/BMAL1 heterodimer induced activation of the Serpine1 promoter through E-box, this may lead to an increased risk of cardiovascular disorders during early morning hours." (PMID 34014841, 2021). "Especially, mutations in BMAL1 or its partner CLOCK could lead to cardiovascular disease." (PMID 35996077, 2022). "Consistently, the circadian gene mutant mice, including ClockΔ19, Bmal1−/−, and Rev-erbα−/− mice, are all hyperlipidemic and prone to cardiovascular diseases." (PMID 34447794, 2021). "As for Bmal1, the core circadian gene, it plays a critical role in lipid metabolism, inflammation, and related cardiovascular diseases." (PMID 34447794, 2021). "Considering the close relationship between circadian clock and cardiovascular diseases, we were wondering whether Bmal1 plays a role in critical limb ischemia." (PMID 34447794, 2021).
neurological disease (6 papers, 2020 to 2025). "Indeed, loss of BMAL1 in astrocytes promotes neuronal death in vitro to influence many aspects of brain function and neurological disease." (PMID 31833591, 2020). "Growing scientific evidence shows that BMAL1 is an important factor for neuroprotection, and its disruption is involved in the development of several nervous system diseases." (PMID 41440117, 2025). "Our findings emphasize that the effects of BMAL1 in neurological disease models are highly cell type and context dependent." (PMID 38032732, 2024). "Further division of related studies based on brain region or different cellular subpopulations will help to better define the regulatory role of the Bmal1 gene in neurological diseases." (PMID 36593479, 2023). "Bmal1 has also been observed to influence different interactions responsible for the onset of neurological disease in animals." (PMID 36593479, 2023). "Together, Bmal1 can function as a biological clock regulator, but its dysfunction can trigger other neurological disorders, both in neurons and glial cells." (PMID 36593479, 2023). "Thus, proper therapeutic modulation of BMAL1 activity is a promising approach for improving nervous system disorders." (PMID 41440117, 2025). "The high level of evolutionary conservativity of BMAL1 in different vertebrate species allows for the creation of valid animal models and the study of BMAL1 molecular functions in physiological and pathological conditions, including human nervous system diseases (Table A1)." (PMID 41440117, 2025). "However, considerable work is still needed to comprehensively depict the mechanisms by which Bmal1 could mediate the development of neurological disorders." (PMID 36593479, 2023).
cardiac disease (5 papers, 2020 to 2025). "In this study, we successfully established BMAL1 KO hESC cell lines and derived human BMAL1-deficient cardiomyocytes to mimic heart disorders associated with circadian malfunction." (PMID 32277346, 2020). "With further research on BMAL1 and its associated pathways, we hope to develop new therapeutic tools to regulate the biological clock, improve cardiac metabolism, reduce inflammatory responses, and, ultimately, improve the prognosis of heart disease." (PMID 40429770, 2025). "Future research needs to focus on the specific mechanisms of action of BMAL1 and how to treat heart disease by interfering with these mechanisms." (PMID 40429770, 2025). "The regulation of apoptosis and autophagy further revealed the role of BMAL1 in cardiac diseases." (PMID 40429770, 2025). "There are also some limitations in the research on the regulatory role of BMAL1 in heart diseases." (PMID 40429770, 2025). "Heart disease could result from a malfunction in the core clock gene BMAL1, according to studies conducted on animals and humans in vitro and in vivo." (PMID 35996077, 2022). "Moreover, cardiomyocyte-specific Bmal1 KO mice also gradually developed into dilated heart disease with age, partly through depressed glucose utilization as well as other cytologic mechanism related to metabolic malfunction." (PMID 32277346, 2020). "BMAL1, as an important core gene in the negative feedback loop, is placed upstream of the biological clock genes and is directly tightly associated with the progression of cardiac diseases, and its deletion can result in permanent loss of cardiac circadian rhythms." (PMID 40429770, 2025).
skin disorder (4 papers, 2010 to 2024). Any deviation from the normal structure or function of the skin or subcutaneous tissue that is manifested by a characteristic set of symptoms and signs. "Because among clock components BMAL1 has a direct effect on skin aging, it likely acts to connect this skin disorder to circadian clock." (PMID 36249807, 2022). "Because among clock components, BMAL1 (and its partner CLOCK) has a direct effect on skin aging (via direct regulation of antioxidant enzymes and thus of ROS elimination), it most likely acts to connect this skin disorder to circadian clock." (PMID 36618934, 2022).
bacterial infection (3 papers, 2020 to 2025). "Nevertheless, the mechanisms underlying the functional role of BMAL1 in affecting coagulation in bacterial infection, such as S. oralis, remain largely obscure." (PMID 33042871, 2020). "However, the distance increased in the two groups after bacterial infection and was even greater in the Bmal1- group." (PMID 40008712, 2025). "Furthermore, the interaction between Bmal1 of hepatocytes and bacterial infection revealed that the expression of BMAL1 descended at the transcriptional level both in vitro and in vivo in the microorganism." (PMID 33042871, 2020). "However, myeloid cell Bmal1 deletion protects against bacterial infection in the lung." (PMID 33363534, 2020).
hematologic malignancies (3 papers, 2015 to 2021). "Bmal1 is a key component in hematologic malignancies, and the inactivation of BMAL1 promotes the progression of hematologic malignancies by disrupting the cellular circadian rhythm and impairing the characteristic circadian clock expression pattern of genes, including C-MYC, catalase, and p300." (PMID 33752691, 2021).
inflammation (3 papers, 2018 to 2024). Aberrant reaction of the microcirculation characterized by movement of fluid and leukocytes from the blood into extravascular tissues. "This disruption has been shown to cause a downregulation in the expression of Arntl (BMAL1), a core circadian clock gene, and leads to lung inflammation and injury through the increased release of the proinflammatory cytokines CCL1 and CXCL." (PMID 39273313, 2024). "Previous studies have shown that dampening of the pulmonary clock through smoking significantly reduces Bmal1 gene expression in the lung, exacerbating lung inflammation, of which excessive neutrophil recruitment is a crucial feature." (PMID 36624683, 2023). "We have previously defined the role of BMAL1, the only essential core clock component for cell-autonomous oscillations, in pulmonary inflammation and immunity." (PMID 29533925, 2018).
kidney disease (2 papers, 2022 to 2025). "Research has highlighted the important role of the circadian gene Bmal1 in the progression of renal diseases." (PMID 39858471, 2025). "In the context of AAI-induced renal injury, Wang Y. and colleagues found that REV-ERBα was upregulated in the kidneys of mice with AAI nephropathy, while its target BMAL1 was downregulated." (PMID 39858471, 2025). "BMAL1 is the main transcriptional activator of the circadian clock, which has been shown to regulate the progress of various renal diseases." (PMID 35174626, 2022). "Additionally, we highlighted gaps in the existing research and examined the potential of Bmal1 as a therapeutic target in kidney disease management." (PMID 39858471, 2025). "This work aims to provide meaningful insights for future studies on the role of the circadian gene Bmal1 in the transition from AKI to CKD, with the goal of identifying therapeutic approaches to mitigate kidney disease progression." (PMID 39858471, 2025). "Thus, targeting Bmal1 could represent a new therapeutic avenue for treating renal diseases." (PMID 39858471, 2025).
neurodevelopmental disorder (2 papers, 2020 to 2025). A behavioral and cognitive disorder with onset during the developmental period that involves impaired or aberrant development of intellectual, motor, or social functions. "We suggest that ultrarare variants in the BMAL1 core clock gene contribute to a neurodevelopmental disorder." (PMID 40720646, 2025). "While common population variants in BMAL1 have been associated with a variety of human disorders, we now implicate rare heterozygous pathogenic variants in BMAL1 as a cause of a Mendelian neurodevelopmental disorder." (PMID 40720646, 2025).
Retinopathy (2 papers, 2022 to 2025). "And th review provides a comprehensive analysis of the underlying mechanisms of the clock gene Bmal1 in other diseases, with the aim of offering insights into innovative therapeutic strategies for retinopathy." (PMID 41243864, 2025). "Accordingly, in animals with oxygen-induced retinopathy, loss of Bmal1 causes a drastic reduction in neovascularization." (PMID 35933488, 2022). "Therefore, we intend to elucidate several mechanisms underlying retinopathy amenable to Bmal1 gene regulation." (PMID 41243864, 2025). "Consequently, achieving a deeper understanding of the association between the clock gene Bmal1, gut microbiome, and the immune microenvironment holds considerable potential for the treatment of retinopathies." (PMID 41243864, 2025). "Herein, we introduce recent advances in circadian rhythms, with a particular focus on the role of Bmal1 in the physiopathology of retinopathy." (PMID 41243864, 2025). "We further summarize the potential therapeutic strategies targeting the Bmal1 and delve into the future perspectives and limitations of circadian clock gene therapy for retinopathy." (PMID 41243864, 2025). "Another pioneering research project has also shown that Bmal1 can affect the prognosis of retinopathy through modulating specific pathophysiological processes." (PMID 41243864, 2025). "This further emphasizes the crucial importance of investigating the intricate correlation between Bmal1 and retinopathy to achieve a more profound understanding of the circadian‐related disorders." (PMID 41243864, 2025). "In these animals the retinopathy is induced during development and thus it can be argued that Bmal1 is important during development." (PMID 35933488, 2022). "Silencing of the retinal clock through targeting neuronal Bmal1 could constitute an approach to treating some forms of retinopathy." (PMID 35933488, 2022). "However, the precise impact of the Bmal1 gene on retinopathy remains elusive." (PMID 41243864, 2025).
bone cysts (1 paper, 2021). "Overexpression of Bmal1 in BMSCs promoted cell migration ex vivo, and transplantation of clock-enhanced BMSCs in the TMJ cavity showed good regenerative effects on articular cartilage and reduced the subchondral bone cysts." (PMID 34638972, 2021).
endocrine diseases (1 paper, 2021). "Circadian clock-independent AS events that play an important role in the homeostasis of the endocrine system, such as alternatively spliced Clock and Bmal1, are regulated by thyroid hormone receptor-associated protein 3 (THRAP3) and are closely associated with endocrine diseases including PTC." (PMID 34722250, 2021).
head and neck tumor (1 paper, 2016). "Interesting, head and neck tumor cell lines present different levels of BMAL1 upon administration of forskolin." (PMID 27285754, 2016).
myopathies (1 paper, 2017). "RNA seq analysis of muscle samples from patients with collagen VI myopathies have linked aberrant circadian regulation to deregulation of autophagy genes, with the effect on collagen VI regulation mirrored in Bmal1 knockout mice." (PMID 29215066, 2017).
reproductive diseases (1 paper, 2022). "Moreover, accumulating clinical evidence has suggested that BMAL1 also participates in human reproductive diseases, suggesting BMAL1 as a potential theraputic target for related reproductive diseases." (PMID 35311235, 2022). "It is anticipated that a deeper understanding of the role of BMAL1 in reproduction could be applied to clinical practices in reproductive disease pathology and target therapies in the future." (PMID 35311235, 2022). "Furthermore, dysfunctional BMAL1 was demonstrated to participate in human reproductive diseases." (PMID 35311235, 2022). "Importantly, BMAL1 also participates in pathogenesis of human reproductive diseases." (PMID 35311235, 2022).
vascular disorder (1 paper, 2025). A general term used to describe any disease affecting blood vessels]. "Alterations of CLOCK, Bmal1, PER1, and PER2 has been observed in the placental cells of pregnant women with vascular disorders like pre-eclampsia." (PMID 40137423, 2025).
BMAL1 also shares sentences with these, for which no sentence is quoted: acute myocardial infarction (5 papers); Parkinson’s (4); alcoholic fatty liver disease (2); anxiety disorder (2); bone osteosarcoma (2); Burkitt lymphoma (2); colorectal tumors (2); gestational diabetes (2); Hodgkins lymphoma (2); Huntington disease (2); immune dysfunction (2); kidney damage (2); mental disorder (2); non-Hodgkin lymphoma (2); non‐alcoholic steatohepatitis (2); ovarian tumor (2); prediabetes (2); tauopathy (2); tuberous sclerosis complex (2); Abdominal obesity (1); Acidosis (1); adenocarcinoma (1); advanced sleep phase syndrome (1); alpha-synucleinopathy (1); arachnodactyly (1); Ataxia (1); benign tumors (1); blood cancers (1); blood pressure (1); brain infarction (1).
A further 50 diseases each share a sentence with BMAL1 in 1 paper.